ITGAL (integrin subunit alpha L)
Diseases named in the same sentence as ITGAL in open-access papers (continued):
Sharing a sentence is not in itself a finding about the gene and the disease.
lung carcinoma (6 papers, 2013 to 2024). "As of 12 August 2023, PubMed listed five articles under the search term of “ITGAL AND Lung cancer”, which studied ITGAL’s biomarker values in NSCLC and its association with CD4 memory cells in the TME of LUAD." (PMID 37835514, 2023). "Finally, our results showed that the protein expression level of ITGAL was significantly higher in stage I tumors than in stage II or III–IV tumors, indicating that ITGAL was associated with the progression of lung cancer, including disease stage and degree of tumor differentiation." (PMID 38646528, 2024). "Immunohistochemical results of ITGAL immunohistochemistry of lung cancer tissue microarrays and their relationship with clinic pathophysiological factors." (PMID 38646528, 2024). "Immunohistochemical results of ITGAL immunohistochemistry of lung cancer tissue microarrays and their relationship with staining results of various indicators in tumor tissues." (PMID 38646528, 2024). "More importantly, compared to normal lung epithelial cells, ITGAL levels in lung cancer tumor cell lines are abnormally decreased." (PMID 37256932, 2023). "The results of current research indicate that ITGAL can be identified as a prognostic indicator of lung cancer, and patients with high expression of ITGAL have a better prognosis." (PMID 36408131, 2022). "Pathways enriched by high expression of ITGAL are mainly related to immune cell recognition and killing of lung cancer cells." (PMID 36408131, 2022). "For example, the CD8, CD20, CD68, and CD4-positive exclusion group had the lowest degree of ITGAL-expressing cell infiltration in lung cancer tissues, whereas the inflamed group had the highest degree of ITGAL-expressing cell infiltration in lung cancer tissues." (PMID 38646528, 2024). "Using the HPA database, we confirmed that ITGAL was significantly down in lung cancer tissue." (PMID 37256932, 2023). "However, the potential mechanisms of ITGAL involved in lung cancer malignant progression and immune immunotherapy of NSCLC are still unknown." (PMID 37256932, 2023). "To explore the mechanism of abnormally low expression of ITGAL in lung cancer, we used multiple comprehensive analyses and successfully found that lncRNA PCBP1-A1 may be down-regulated ITGAL expression via inhibited the expression of miR-9-5p and miR-424-5." (PMID 37256932, 2023). "However, the DNA methylation level of the ITGAL gene did not affect the prognosis of lung cancer patients." (PMID 37256932, 2023).
periodontitis (6 papers, 2017 to 2025). An acute or chronic inflammatory process that affects the tissues that surround and support the teeth. "ITGAL, a protein interacting with PC unique terpenes, is a key gene closely related to oxidative stress damage in periodontitis." (PMID 38731856, 2024). "BTK and ITGAL were found to be the most important cross-signaling genes between periodontitis and atherosclerosis by WGCNA combined with immune cell analysis." (PMID 37369700, 2023). "We verified the expression levels of two crosstalk genes separately in the validation dataset, and the results showed that BTK and ITGAL were upregulated in both atherosclerosis and periodontitis." (PMID 37369700, 2023). "We found that ITGAL showed a significant positive correlation with Macrophages M0 and T cells gamma delta in both periodontitis and atherosclerosis samples, suggesting that ITGAL plays an equal role in the immune regulation of both diseases." (PMID 37369700, 2023). "We then further validated the diagnostic effect of both genes in the validation dataset: BTK (AUC = 0.861) and ITGAL (AUC = 0.832) in atherosclerosis; and BTK (AUC = 0.810) and ITGAL (AUC = 0.835) in periodontitis." (PMID 37369700, 2023). "Six of them were identified as key OS-genes (CXCR4, SELL, FCGR3B, FCGR2B, PECAM1, and ITGAL) in periodontitis." (PMID 36148415, 2022). "In the present study, by performing multiple bioinformatics analysis methods, we firstly identified six key OS-genes (CXCR4, SELL, FCGR3B, FCGR2B, PECAM1, and ITGAL) in periodontitis, whose expression levels were significantly upregulated." (PMID 36148415, 2022). "ITGAL has been less studied in periodontitis and atherosclerosis." (PMID 37369700, 2023). "We further evaluated the diagnostic sensitivity and specificity of both genes by ROC curves, and both genes had good diagnostic value in the experimental set: BTK (AUC = 0.909) and ITGAL (AUC = 0.937) in atherosclerosis; BTK(AUC = 0.840) and ITGAL(AUC = 0.873)in periodontitis." (PMID 37369700, 2023).
non-small cell lung carcinoma (5 papers, 2018 to 2025). A group of at least three distinct histological types of lung cancer, including non-small cell squamous cell carcinoma, adenocarcinoma, and large cell carcinoma. "In contrast, our study found that non-small-cell lung cancer expressed low levels of ITGAL, while controls expressed high levels." (PMID 38646528, 2024). "However, experimental studies targeting ITGAL and immune cell infiltration in non-small-cell lung cancer (NSCLC) and the response to immune checkpoint inhibitor therapy are lacking." (PMID 38646528, 2024).
asthma (4 papers, 2006 to 2022). "As the targets proteomic analysis located, ITGAL, Syk, and Vav1 remain crucial in the immune regulation of airway inflammation in asthma, particularly T cell regulation." (PMID 36329800, 2022). "We suspected that CAG suppressed the upstream targets ITGAL and Syk and the downstream target Vav1 to decrease the excessive infiltration of leukocytes in the formation of asthma." (PMID 36329800, 2022). "We also simulated the potential binding sites between CAG and ITGAL, Syk, and Vav1 to further confirm that these 3 targets remain important in the therapeutic effects of CAG in asthma." (PMID 36329800, 2022).
atherosclerosis (4 papers, 2019 to 2023). A disease characterized by the build-up of fatty material and calcium deposition in the arterial wall resulting in partial or complete occlusion of the arterial lumen. "A predictor of atherosclerosis progression, ITGAL, was also found to correlate with both [64Cu]-Cu-DOTA-TATE and Na[18F]F." (PMID 37286582, 2023). "Although no studies have reported that ITGAL is directly related to the development of FH or atherosclerosis." (PMID 32938406, 2020).
breast carcinoma (4 papers, 2017 to 2024). "Some SNPs in six immunological genes, BTLA, ITGAL, CTLA4, ICOS, PDCD1, and VTCN1 were reported as breast cancer risk mutations in previous studies." (PMID 27911271, 2017). "Moreover, breast cancer–infiltrating Tregs showed markedly higher expression of ITGAL compared with peripheral Tregs from the same patient cohort." (PMID 38787791, 2024).
glioblastoma (4 papers, 2022 to 2023). The most malignant astrocytic tumor (WHO grade IV). "Similarly, integrins CD49a (ITGA1), CD49d (ITGA4), CD51 (ITGAV), and CD11a (ITGAL) were selected for further validation based on elevated gene expression in glioblastoma-infiltrating T cells." (PMID 35464424, 2022).
inflammatory bowel disease (4 papers, 2017 to 2025). A spectrum of small and large bowel inflammatory diseases of unknown etiology. "The upregulated expression of ITGAL correlated with the risk of inflammatory bowel disease (IBD) and increased levels of proinflammatory cell surface markers in response to stimulus." (PMID 35999614, 2022). "Supporting this hypothesis, a prior genome-wide association study identified associations between inflammatory bowel disease susceptibility and increased immune activation of specific integrin genes (ITGA4, ITGB8, ITGAL, and ICAM1)." (PMID 39982236, 2025).
lung squamous cell carcinoma (4 papers, 2018 to 2024). "Similarly, in lung squamous cell carcinoma, patients with higher expression of the ITGAL gene had longer OS time (HR=0.73, P=1.7e-03) and PFS time (HR=0.55, P=3.7e-03)." (PMID 38646528, 2024).
metastatic melanoma (4 papers, 2020 to 2023). A melanoma that has spread from its primary site to another anatomic site. "The integrin LFA-1 (also known as ITGAL), also known as CD11a, is upregulated in metastatic melanoma, highly expressed in most immune cell populations." (PMID 35681821, 2022). "ITGAL, also known as CD11a, is upregulated in metastatic melanoma, highly expressed in most immune cell populations, and encodes a subunit of LFA-1 integrin." (PMID 33336008, 2020). "Survival and multivariate Cox regression analyses revealed four vital genes, namely, POU2AF1, ITGAL, CXCR2P1, and MZB1, that affect the prognosis of patients with metastatic melanoma." (PMID 33336008, 2020). "ITGAL can promote an increase in the ratio of CD4 and CD8 T cells, improving the survival rate of patients with metastatic melanoma, which may explain why high expression of ITGAL is associated with a better prognosis." (PMID 37388230, 2023).
Obesity (4 papers, 2018 to 2024). Accumulation of substantial excess body fat. "The abundance of different obesity related proteins such as LEP, ITGAL, IKBIP, H2-AA, TAP2 and FABP5 was very low in AdEVs from lean mice and was detected in only one or no biological replicate." (PMID 36759608, 2023).
ovarian carcinoma (4 papers, 2015 to 2024). A malignant neoplasm originating from the surface ovarian epithelium. "Furthermore, ITGAL is associated with poor prognosis in ovarian cancer, while it also suggests better prognosis and inhibits tumor proliferation in NSCLC." (PMID 39605903, 2024). "Although ITGAL has not been thoroughly investigated, it is known that the carcinogenic potential of ITGAL, whose expression levels of ITGAL plays a crucial role in carcinogenic potential, was correlated with renal cancer, ovarian cancer, colorectal cancer, and head and neck squamous cell carcinoma." (PMID 35399517, 2022). "By screening 31 drugs with 110 targets, FNTA, HSPA5, NEU1, CCND1, CASP1, CASP3 were negatively correlated with ovarian cancer, and HMGCR, PLA2G4A, ITGAL, PTGS1, FNTB were positively correlated with ovarian cancer." (PMID 38651149, 2024). "Among them, FNTA, HSPA5, NEU1, CCND1, CASP1, CASP3 had a negative causal association with ovarian cancer development, and HMGCR, PLA2G4A, ITGAL, PTGS1, FNTB had a positive causal association with ovarian cancer development." (PMID 38651149, 2024).
viral infection (4 papers, 2005 to 2025). "To further investigate the impact of THBS1 and ITGAL on WT virus replication, we overexpressed these two genes in Vero E6 cells prior to viral infection and monitored viral replication levels at 12, 24, 48, and 72 hpi." (PMID 40927453, 2025).
colorectal cancer (3 papers, 2019 to 2024). A primary or metastatic malignant neoplasm that affects the colon or rectum. "In current oncology studies, expression of the ITGAL gene has been associated with the progression and aggressiveness of renal, ovarian and colorectal cancers." (PMID 38646528, 2024).
diabetes (3 papers, 2015 to 2025). "Transferring splenocytes lacking ItgaL to NOD/Rag-1 experimental mice does not lead to the development of diabetes, which suggests that ItgaL has a role in NOD/LtJ T cell activation." (PMID 32938406, 2020).
glioma (3 papers, 2023 to 2025). A benign or malignant brain and spinal cord tumor that arises from glial cells (astrocytes, oligodendrocytes, ependymal cells). "ITGAL/CD11a demonstrates marked enrichment in glioma-associated microglia/macrophages (GAMs) derived from both murine models and human LGG specimens." (PMID 40838069, 2025). "In glioma, results show that ITGAL is up-regulated and knockout ITGAL inhibited CX3CL1-directed motility." (PMID 37256932, 2023). "Previous studies showed that ITGAL was elevated in glioma and knockdown of ITGAL inhibited glioma cell growth." (PMID 37256932, 2023).
head and neck squamous cell carcinoma (3 papers, 2020 to 2024). A squamous cell carcinoma that arises from any of the following anatomic sites: lip and oral cavity, nasal cavity, paranasal sinuses, pharynx, larynx, and salivary glands. "ITGAL is also involved in immune response, inflammatory response, and formation of the tumor microenvironment, thus contributing to the pathogenesis of head and neck squamous cell carcinoma." (PMID 33336008, 2020).
acute myeloid leukemia (2 papers, 2022 to 2023). Acute myeloid leukemia (AML) is a group of neoplasms arising from precursor cells committed to the myeloid cell-line differentiation. "It has been confirmed that ITGAL is related to poor prognosis and immunity in acute myeloid leukemia." (PMID 37256932, 2023).
bladder cancer (2 papers, 2023 to 2024). "The functional role of ITGAL in bladder cancer has not been focused on and is a potential research direction." (PMID 37324016, 2023). "Our analysis of BLCA samples in the combined TCGA and GTEx databases revealed that ITGAL was significantly low expressed in bladder cancer tissues (data not shown), suggesting that ITGAL may have a different regulatory mechanism in bladder tumors." (PMID 37324016, 2023).
endometriosis (2 papers, 2021 to 2025). The growth of functional endometrial tissue in anatomic sites outside the uterine body. "Some of them, such as Rap1 pathway and leukocyte transendothelial migration pathway(including Intercellular Adhesion Molecule 1[ICAM-1) and Integrin Subunit Alpha L (ITGAL)], have been proven as involved in endometriosis." (PMID 34122342, 2021).
helminth infection (2 papers, 2010 to 2020). "ITGAL and ITGAM are bound by neutrophil inhibitory factor (NIF), an antiadhesive glycoprotein isolated from the canine hookworm Ancylostoma caninum, suggesting that leukocyte integrins are relevant to the immune response to helminth infections." (PMID 20807397, 2010).
lymphoma (2 papers, 2021 to 2025). A malignant (clonal) proliferation of B- lymphocytes or T- lymphocytes which involves the lymph nodes, bone marrow and/or extranodal sites. "BJAB lymphoma cells express low levels of ITGAL as partner of ITGB2 in LFA-1, and intermediate levels of ITGAM." (PMID 40464949, 2025).
prostate carcinoma (2 papers, 2020 to 2024). A carcinoma that arises from epithelial cells of the prostate gland. "In the research of prostate cancer, the expression of ITGAL, along with four other genes, is connected with a number of positive lymph nodes." (PMID 33336008, 2020).
ZIKV infection (2 papers, 2017 to 2025). "Moreover, by understanding how mosquito cells respond to ZIKV infection, some key genes such as ITGAL, CXCL8, and THBS1 may be targeted to disrupt the virus’s replication or transmission." (PMID 40927453, 2025).
autism (1 paper, 2023). Persistent deficits in social interaction and communication and interaction as well as a markedly restricted repertoire of activity and interest as well as repetitive patterns of behavior. "More notably, LAMP1 also interact with ITGAL, FYN and FERMT3 which were dysregulated in our blood biomarker screening results, suggesting that these proteins involved in focal adhesion and immune regulation may play a vital role in autism." (PMID 37640746, 2023).
Cluster headache (1 paper, 2025). A type of headache characterized by repeated attacks of unilateral pain lasting 15 to 180 minutes and associated with local autonomic signs. "Lastly, they expanded their analysis to include ANO3, ITGAL, PLCE1, and PCDHB6 genes and found rs1531394 in the ANO3 gene to be significantly associated with cluster headache." (PMID 39560176, 2025).
diseases of the thymus (1 paper, 2021). "In contrast, PheWAS analysis of a common binding site variant in ITGAL (rs1064524), encoding integrin α L, revealed strong associations with pleural plaques, dense hyalinized collagen fibers formed in parietal pleura, and diseases of the thymus." (PMID 34516913, 2021). "Notably, we found that rs1064524 in ITGAL [minor allele frequency (MAF)Biobank = 4.3%] associated with phenome-wide significance (Bonferroni correction) with pleural plaques (β = 1.9; P = 7.5 × 10−7) and diseases of the thymus (β = 1.5; P = 4.5 × 10−5)." (PMID 34516913, 2021).
fibrosarcoma (1 paper, 2021). A malignant mesenchymal fibroblastic neoplasm affecting the soft tissue and bone. "The anti-tumor role of ITGAL has been confirmed in fibrosarcoma." (PMID 34633989, 2021).
gastric adenocarcinoma (1 paper, 2024). "Upregulation of ITGAL expression was strongly associated with immunomodulators, chemokines, and levels of CD8+ T cells, CD4+ T cells, B cells, monocytes, neutrophils, macrophages, T cells, natural killer (NK) cells, and myeloid dendritic cell infiltration in gastric adenocarcinomas (STAD)." (PMID 38646528, 2024).
glomerulonephritis (1 paper, 2020). A renal disorder characterized by damage in the glomeruli. "The renal level of ITGAL was positively correlated with glomerular pathology, suggesting that tRA post-treatment may have protected against glomerulonephritis even though the benefit was not obvious." (PMID 32265909, 2020).
head and neck cancer (1 paper, 2024). A primary or metastatic malignant neoplasm affecting the head and neck. "The classification of HNSCC according to the effect of ITGAL on the immune microenvironment also shows that ITGAL can affect the prognosis of head and neck cancer through the immune microenvironment." (PMID 39605903, 2024).
Hyperglycemia (1 paper, 2020). An increased concentration of glucose in the blood. "In addition, there are reports that using ItgaL−/−null NOD/LtJ mice, genetic defects of ItgaL can prevent the occurrence of hyperglycemia." (PMID 32938406, 2020).
Insulin resistance (1 paper, 2020). Increased resistance towards insulin, that is, diminished effectiveness of insulin in reducing blood glucose levels. "Animal experiments have shown that lack of ItgaL can prevent insulin resistance, while lack of Itgb2 can provide protection." (PMID 32938406, 2020).
leprosy (1 paper, 2017). Leprosy is a chronic infectious disease affecting primarily the skin and peripheral nervous system. "Similarly, 7 of the 9 SNPs significantly heterogeneous between T1R and leprosy were eQTLs in either whole blood, rs3774937 (NFKB1), rs10065637 (ANKRD55), rs11150589 (ITGAL) and rs2836878 (lncRNA ENSG00000235888) or multiple tissues, rs4664304 (LY75), rs113653754 (HLA-DQB1) and rs4768236 (LRRK2)." (PMID 28222097, 2017).
pancreatic ductal adenocarcinoma (1 paper, 2019). An infiltrating adenocarcinoma that arises from the epithelial cells of the pancreas. "In pancreatic ductal adenocarcinoma, ITGAL, which encodes another adhesion molecule and is also shown in our miRNA-mRNA networks, was over-expressed in tumor cells." (PMID 31150430, 2019).
pulmonary arterial hypertension (1 paper, 2023). Pulmonary arterial hypertension (PAH) is a group of diseases characterized by mean pulmonary artery pressure >20 mmHg and elevated pulmonary arterial resistance leading to right heart failure. "This approach was used in a paper from this year that shows significant upregulation of SOCS3, ITGAL, NFIC, NCOR2, and PGK1 mRNA (qRT-PCR) in peripheral blood mononuclear cells from pulmonary arterial hypertension (PAH) patients compared to healthy controls (p ≤ 0.05)." (PMID 37762023, 2023).
pyometra (1 paper, 2023). "As immunosuppressive agents, cyclosporine and sirolimus are expected as ITGAL gene targets to suppress inflammation caused by pyometra." (PMID 37101686, 2023).
renal cell carcinoma (1 paper, 2021). "ITGAL encodes the alpha L chain and its expression has been previously linked to renal cell carcinoma." (PMID 33933144, 2021).
steatosis (1 paper, 2022). Increased lipid within the cytoplasm of cells. "To confirm these conclusions in vitro, we cultured HDF cells and induced steatosis using sodium palmitate (10 mmol/L) and sodium oleate (10 mmol/L) for 24 h, and detected expression levels of ITGAM, ITGAL, and NLRC4 in cells." (PMID 36457728, 2022).
Thrombocytopenia (1 paper, 2015). A reduction in the number of circulating thrombocytes. "For other adhesion molecules, integrin alpha L chain (ITGAL) and integrin α2β1 has been found a higher probability to involve in severe thrombocytopenia in vivax malaria." (PMID 25889165, 2015).